PIM3 (Pim-3 proto-oncogene, serine/threonine kinase)
Description:
Proto-oncogene with serine/threonine kinase activity that can prevent apoptosis, promote cell survival and protein translation. May contribute to tumorigenesis through: the delivery of survival signaling through phosphorylation of BAD which induces release of the anti-apoptotic protein Bcl-X(L), the regulation of cell cycle progression, protein synthesis and by regulation of MYC transcriptional activity. Additionally to this role on tumorigenesis, can also negatively regulate insulin secretion by inhibiting the activation of MAPK1/3 (ERK1/2), through SOCS6. Involved also in the control of energy metabolism and regulation of AMPK activity in modulating MYC and PPARGC1A protein levels and cell growth.
Synonyms: pim-3
Tractability: Small molecule: a drug acting on it is in phase 1 trials; a high-quality ligand is known; it belongs to a druggable protein family. PROTAC: UniProt records ubiquitination sites on it; ubiquitination databases record sites on it; a small molecule that binds it is known.
Target class: Kinase; Protein Kinase; CAMK protein kinase group; Enzyme; CAMK protein kinase PIM family
Chemical probes: LGH-447 (high quality), PD083749, PD084414
Gene: Protein-coding gene on chromosome 22 (49,960,463 to 49,964,075, forward strand). Ensembl gene ENSG00000198355.
Subcellular location: Cytoplasm
Subcellular location (Human Protein Atlas): Cytosol
Gene Ontology:
Molecular function: protein binding; protein serine/threonine kinase activity; ATP binding; protein kinase activity; protein serine kinase activity
Biological process: negative regulation of apoptotic process; regulation of mitotic cell cycle; negative regulation of insulin secretion involved in cellular response to glucose stimulus; cellular response to forskolin
Cellular component: cytosol; cytoplasm
Genetic constraint (gnomAD): Loss-of-function variants: 13 observed, 20.62 expected, observed/expected ratio (o/e) 0.63, 90% interval 0.41 to 1. The synonymous counts are far from expectation, so gnomAD's model fits this gene poorly and the ratio says little. Missense variants: 482 observed, 411.69 expected, observed/expected ratio (o/e) 1.17, 90% interval 1.09 to 1.26. Synonymous variants: 341 observed, 205.63 expected, observed/expected ratio (o/e) 1.66, 90% interval 1.52 to 1.81.
Homologues: Orthologues: mouse Pim3 (96% identical), rat Pim3 (96% identical), dog PIM3 (95% identical), pig PIM3 (95% identical), guinea pig PIM3 (94% identical), macaque PIM3 (93% identical), chimpanzee PIM3 (83% identical), tropical clawed frog pim3 (78% identical), zebrafish pim3 (72% identical). Paralogues in human: PIM1 (66% identical), PIM2 (56% identical).
Diseases named in the same sentence as PIM3 in open-access papers:
PIM3 is named in the same sentence as 77 diseases in open-access papers, as found by Europe PMC text mining. Sharing a sentence is not in itself a finding about the gene and the disease. The quoted sentences say what the papers report.
pancreatic cancer (16 papers, 2011 to 2024). "Pim-3 protein was expressed at high levels in 54.7% (58/106) of the pancreatic cancer tissues, and Kaplan-Meier analysis indicated that high Pim-3 expression was associated with a poor prognosis in 79 pancreatic cancer patients." (PMID 25971209, 2015). "Another study on pancreatic cancer investigated the role of PIM3 in vivo and the underlying PIM3 signaling regulatory mechanisms using established MiaPaca-2 cells overexpressing wild-type PIM3 or K69M-PIM3 cells." (PMID 38339286, 2024). "PIM3 has been shown to be the primary factor driving colon and pancreatic cancer growth by inhibiting the pro-apoptotic activity of BAD by inducing phosphorylation at BAD Ser155." (PMID 38339286, 2024). "In the context of radiotherapy, ionizing radiation has been found to induce PIM3 in pancreatic cancer cells, leading to radioresistance in both in vitro and in vivo tumor models." (PMID 38339286, 2024). "Previous studies considered PIM3 as a gene closely related to the occurrence of various cancers such as colon cancer, liver cancer, pancreatic cancer, prostate cancer, gastric cancer, and breast cancer." (PMID 39092429, 2024). "Stable overexpression of PIM3 in pancreatic cancer cells dramatically reduced the DNA damage response and G2/M-phase cell cycle arrest, protecting cells from radiation therapy." (PMID 38339286, 2024). "MiR-33a and miR-574-3p were shown to downregulate Pim-3 expression in human colorectal and pancreatic cancer cells, respectively." (PMID 39507762, 2024). "At present, a large number of studies have shown that PIM-3 is mainly over-expressed in solid tumors, such as lung cancer, gastric cancer, pancreatic cancer, colorectal cancer, liver cancer, and prostate cancer." (PMID 36871027, 2023). "PIM3 overexpression induced stemness in pancreatic cancer cells via the activation of the STAT3 pathway." (PMID 35892829, 2022). "Other investigators demonstrated that miR-33 targets PIM3 mRNA and that the overexpression of miR-33a in pancreatic cancer cell lines suppressed PIM3 expression." (PMID 35892829, 2022). "It increased the angiogenesis of pancreatic cancer cells partially through transcriptional regulation of PIM3, a proto-oncogene with serine/threonine kinase activity." (PMID 28587243, 2017). "PIM3 is constitutively expressed in pancreatic cancer, where it not only inhibits cell apoptosis by phosphorylating Bad but also promotes pancreatic tumor neoangiogenesis." (PMID 28587243, 2017). "Downregulation of PIM-3 expression can decrease cell proliferation, invasion, chemoresistance, radioresistance and angiogenesis in pancreatic cancer." (PMID 27596051, 2016). "PIM-3 is overexpressed in patients with pancreatic cancer and is a prognostic indicator related to poor survival in these patients." (PMID 27596051, 2016). "Our previous study indicated that Pim-3 is important for cell growth, apoptosis, and cell-cycle progression in human pancreatic cancer, although miR-124 targets Pim-3 in glioblastoma stem cells." (PMID 25971209, 2015). "Consistent with this, we found that miR-33a targeted Pim-3 to increase the chemosensitivity of pancreatic cancer cells and reverse the chemoresistance of pancreatic cancer cells to gemcitabine both in vitro and in vivo." (PMID 25971209, 2015). "The amount of Pim-3 mRNA associated with AGO1 was significantly higher in MiaPaca-2 and PCI55 pancreatic cancer cells transfected with miR-33a mimics than in parental cells or cells transfected with negative control mimics (cel-miR-239b)." (PMID 25971209, 2015). "For example, PIM3 is a proto-oncogene that enhances pancreatic cancer growth by modulating tumor vasculogenesis; PTP4A3 can promote cancer metastasis particularly in colorectal cancers; and TOMM20 expression is associated with tumor size in gastric cancer." (PMID 26253570, 2015). "Taken together, these results indicate that Pim-3 is a true target of miR-33a in pancreatic cancer cell lines." (PMID 25971209, 2015).
pancreatic cancer (continued). "Here, we showed that miR-33a acts as an important suppressor of human pancreatic cancer by directly regulating Pim-3 expression at the post-transcriptional level." (PMID 25971209, 2015). "Plasma miR-33a levels were significantly lower in pancreatic cancer patients with high Pim-3 protein expression than in healthy controls." (PMID 25971209, 2015). "PIM3 has been reported to participate in the development of various cancers, including hematological malignancies, gastrointestinal tumors, pancreatic cancer and hepatocellular carcinoma." (PMID 26039373, 2015). "High Pim-3 expression correlated with a poor prognosis, and plasma miR-33a levels were negatively correlated with the levels of Pim-3 in pancreatic tumors." (PMID 25971209, 2015). "Later studies showed that Pim-3 is activated by the Ets-1 transcription factor in pancreatic cancer cells." (PMID 21646687, 2011). "Overall, combining radiation with PIM3 targeting agents may increase the effectiveness of radiotherapy in patients with pancreatic cancer." (PMID 38339286, 2024). "PIM3 is highly expressed in tumors, such as lymphoma, lung, gastric, liver, and pancreatic cancer." (PMID 36871027, 2023). "The strongest positive contributions, however, do not come from a set of genes with as coherent a functional annotation as the negatives except with regard to insulin trafficking and secretion; BACE2 and PIM-3, which is also known to promote human pancreatic cancer growth." (PMID 26039411, 2015). "Furthermore, we also found that the expression levels of miR-33a in seven pancreatic cancer cell lines were negatively correlated with those of Pim-3 protein (Spearman's r = −0.79, P > 0.05)." (PMID 25971209, 2015). "Moreover, stable expression of miR-33a in pancreatic cancer cells led to a significant downregulation of Pim-3 protein expression and inhibited cancer cell growth both in vitro and in vivo." (PMID 25971209, 2015). "Furthermore, we previously showed that human pancreatic cancer cells express much lower levels of Pim-1 and Pim-2 mRNA than Pim-3 mRNA." (PMID 25971209, 2015). "Notably, plasma miR-33a levels in healthy controls were similar to those in pancreatic cancer patients with low Pim-3 expression; however, plasma miR-33a levels were significantly lower in pancreatic cancer patients with high Pim-3 expression than in controls." (PMID 25971209, 2015). "Furthermore, overexpression of miR-33a in pancreatic cancer cell lines suppressed Pim-3 expression, leading to downregulation of the AKT/Gsk-3β/β-catenin pathway." (PMID 25971209, 2015). "Thus, it is likely that miR-33a inhibits cell growth mainly by binding to Pim-3 in human pancreatic cancer cells." (PMID 25971209, 2015). "Pim-3 expression was a prognostic indicator related to poor survival in pancreatic cancer patients." (PMID 25971209, 2015). "In line with previous reports, we found that the AKT/β-catenin signaling was activated in gemcitabine-resistant pancreatic cancer cells, and that overexpression of miR-33a reversed the increased expression of β-catenin by inhibiting Pim-3/AKT/β-catenin signaling." (PMID 25971209, 2015). "Furthermore, the miR-33a levels in plasma samples from the 106 PDAC patients were negatively correlated with the levels of Pim-3 in the pancreatic tumors." (PMID 25971209, 2015). "Therefore, early examination of miR-33a expression in the plasma and Pim-3 expression in tissues may aid the development of new therapeutic strategies and predict the prognosis of pancreatic cancer." (PMID 25971209, 2015). "According to a previous study, deactivating PIM3 kinase or preventing PIM3 protein production did not affect the overall survivin expression in human pancreatic cancer cells." (PMID 38339286, 2024). "PIM-3 over-expression plays a certain role in the occurrence and development of tumors, and PIM-3 is even related to the prognosis and chemotherapy resistance of pancreatic cancer, liver cancer, and colorectal cancer." (PMID 36871027, 2023).
pancreatic cancer (continued). "Overexpression of miR-33a led to a marked downregulation of Pim-3 expression, thereby inhibiting AKT/Gsk-3β/β-catenin signaling, which in turn reduced cell proliferation and increased the chemosensitivity of pancreatic cancer cells to gemcitabine both in vitro and in vivo." (PMID 25971209, 2015). "Additionally, in prostate cancer (DU45) and pancreatic cancer (MiaPaCa-2) cell lines, PIM3 specifically, but not PIM1 and PIM2, regulates p-STAT3 levels, potentially through its protein tyrosine phosphatase and tyrosine kinase activity." (PMID 38339286, 2024). "Moreover, STAT3 activation induced by Pim-3 increases the transcription of Hif-1α, thereby up-regulating the expression of MDR1 (P-glycoprotein) gene, resulting in reduced chemosensitivity in human pancreatic cancer cells." (PMID 29069816, 2017). "Moreover, transfection of MiaPaca-2 and PCI55 pancreatic cancer cells with miR-33a mimics led to a significant reduction in the expression of Pim-3 protein, but not in Pim-3 mRNA expression." (PMID 25971209, 2015). "Stable expression of miR-33a in SW1990 and MiaPaca-2 pancreatic cancer cells (SW1990-miR-33a and Mia-2-miR-33a) led to a reduction in the level of Pim-3 protein but not that of mRNA." (PMID 25971209, 2015).
hepatocellular carcinoma (11 papers, 2006 to 2023). A malignant tumor that arises from hepatocytes. "Other investigators have found that PIM3, specifically, plays a role in the development of hepatocellular carcinoma, a liver cancer that occurs predominantly in adults." (PMID 29854306, 2018). "Pim3 encodes a kinase that is upregulated in many cancer cell lines and downregulation of PIM3 retarted cell proliferation in human hepatoma cell lines." (PMID 26576534, 2015). "It has also been reported that transgenic mice expressing human Pim3 selectively in the liver have increased frequency and decreased latency of hepatocellular carcinoma induced by the carcinogen diethylnitrosamine." (PMID 23565217, 2013). "These investigators demonstrated that transgenic mice selectively expressing PIM3 in the liver developed hepatocellular carcinoma more frequently than wild type mice, and that inhibition of PIM3 decreased cell proliferation and apoptosis in hepatocellular carcinoma." (PMID 29854306, 2018). "PIM3 levels were also increased to varying degrees by rapamycin treatment in the hepatocellular carcinoma (HCC) lines JHH-4, Hep-G2 and JHH-6, and the breast cancer cell lines MDA-MB-453 and MDA-MB-468." (PMID 29170467, 2017). "Pim‐3 is aberrantly expressed in human HCC tissues and hepatocellular carcinoma cell lines while being involved in the proliferation of human hepatocellular carcinoma cell lines." (PMID 37162273, 2023). "Previously, we reported that therapy with a dual-function small hairpin RNA (shRNA) vector containing a Pim-3-silencing shRNA (sh-Pim-3) and a TLR7-stimulating ssRNA markedly suppressed the growth of murine hepatoma through activating CD4+ T cells and NK cells." (PMID 31849942, 2019). "Recently, over-expression of Pim-3 has been demonstrated in a mouse model of hepatocellular carcinoma, although the functional role of Pim-3 was not determined." (PMID 16403219, 2006).
prostate carcinoma (10 papers, 2011 to 2024). A carcinoma that arises from epithelial cells of the prostate gland. "Higher PIM3 expression is often correlated with shorter overall survival in patients with colorectal, pancreatic, and prostate cancer, hepatoblastoma, and breast cancer." (PMID 38339286, 2024). "Here we show that PC-3 prostate cancer cells overexpressing either Pim-1 or Pim-3 kinases form larger xenograft tumors than the parental PC-3 cells." (PMID 26075720, 2015). "To investigate the ability of Pim-3 to promote tumor growth and metastasis under in vivo conditions, we established a stable PC-3/Pim-3 prostate cancer cell line expressing human Pim-3 together with Tomato as a fluorescent follow-up marker." (PMID 26075720, 2015). "We show here that tumorigenic growth of both subcutaneously and orthotopically inoculated prostate cancer xenografts is enhanced by stable overexpression of either Pim-1 or Pim-3." (PMID 26075720, 2015). "PIM-1 and PIM-2 are implicated in prostate cancer development, PIM-1 is over expressed in head and neck squamous cell carcinoma and bladder cancer and PIM-3 is over expressed in colorectal, pancreatic and hepatocellular carcinoma." (PMID 22193779, 2011). "Previous reports have shown that PIM1 overexpression increased ERK1/2 phosphorylation in prostate cancer cells, increased p38-MAPK activation by phosphorylation in Basophils, and increased activation of JNK in cardiomyocytes by PIM3." (PMID 25238262, 2014). "PIM3 and PIK3C3 in breast cancer, PIM3 and PTEN in breast, kidney, and ovarian cancer, and PIM3 and PTEN in prostate cancer Malignancies of the liver and thyroid, as well as cancers of the breast and ovary, have been linked to PIK3C3 and PTEN mutations in the past." (PMID 35154620, 2022).
breast carcinoma (9 papers, 2010 to 2024). "PIM3 is a serine/threonine kinase linked to various oncogenic processes and often overexpressed in solid cancers such as pancreatic, liver, colon, stomach, and breast cancers." (PMID 38339286, 2024). "PIM3 is a proto-oncogene that is frequently overexpressed in cancers originating from endoderm-derived tissues, such as the liver, pancreas, colon, stomach, prostate, and breast cancer." (PMID 38339286, 2024). "Pim-3 is overexpressed particularly in tumor tissues of endoderm-derived organs such as the liver, pancreas, and colon, as well as in nasopharyngeal carcinoma, prostate and breast cancer, and some sarcomas (i.e., Ewing’s sarcoma)." (PMID 38339286, 2024). "In addition, AKT (Protein kinase B (PKB) signaling pathway downstream targets, e.g., Breast Cancer Anti-estrogen Resistance 1 (Bcar1) and Provirus integrating site Moloney murine leukemia virus 3 (Pim3), were also differentially regulated." (PMID 34884498, 2021). "In various breast cancer cell lines, intrinsic resistance to the PI3Kα or AKT inhibitors has been demonstrated to involve PIM1, with PIM3 likely playing a less prominent role in this setting." (PMID 35440108, 2022).
gastric cancer (8 papers, 2015 to 2025). A primary or metastatic malignant neoplasm involving the stomach. "Previous studies suggest that Pim-3 is also highly expressed in pancreatic and gastric cancers, where it cooperates with c-Myc to promote survival." (PMID 29069816, 2017). "For example, the PIM3 gene, a member of the proto-oncogene PIM family with serine/threonine kinase activity, was related to gastric adenoma-adenocarcinoma sequence and progression in gastric cancer." (PMID 40623120, 2025). "The qRT-PCR experiments were designed to detect the expression levels of the top 5 ranking HAX1, RNF2, PIM3, TPP1 and CAV1 genes in addition to the seed proteins ABCB1, AKT1 and BCL2 in both the SGC7901 gastric cancer cell line and the Adriamycin resistant SGC7901/ADR cell line." (PMID 26039373, 2015).
colorectal cancer (6 papers, 2015 to 2024). A primary or metastatic malignant neoplasm that affects the colon or rectum. "While proviral integration of Moloney murine 3 (PIM3) is associated with Distal Muscular Dystrophy, it has also been demonstrated to function as an oncogenic factor promoting tumor growth in colorectal cancer and hepatoblastoma." (PMID 34777208, 2021). "Chronic inflammation is a driving factor in tumor progression, and PIM3 is significantly overexpressed in UC-related colorectal cancer." (PMID 39092429, 2024). "Until now, very few studies on the function of Pim-3 in metastasis or the response to treatment of colorectal cancer can be found." (PMID 29167471, 2017).